KL (klotho)
Diseases named in the same sentence as KL in open-access papers (continued):
Sharing a sentence is not in itself a finding about the gene and the disease.
emphysema (26 papers, 2010 to 2025). "KL‐deficient mice showed aging phenotypes, such as obvious emphysema and premature senility at the early stage, which are characteristics of COPD." (PMID 39930762, 2025). "Klotho-deficient mice exhibit a remarkable number of important aging features, including a shortened lifespan, sarcopenia, and features of emphysema (increased air spaces, increased expiration time, and damaged alveolar walls)." (PMID 39091285, 2024). "Cigarette smoke decreases klotho expression in primary airway epithelial cells, and klotho-deficient mice develop emphysema and increased airway inflammation." (PMID 35744080, 2022). "In summary, klotho deficient mice show emphysema, lung inflammation and a decrease in ASL depth, CBF resulting in impaired MCT." (PMID 32039219, 2019). "Mice deficient in the Klotho gene show accelerated aging and develop spontaneous emphysema." (PMID 40554265, 2025). "Klotho mice are also more susceptible to developing emphysema after cigarette smoke." (PMID 40554265, 2025). "Some animal studies have suggested that the induction of klotho expression may reverse advanced age-associated emphysema." (PMID 39091285, 2024). "Klotho, an antiaging gene, encodes a membrane-bound protein that may promote epithelial cell viability and protect against emphysema by regulating cigarette smoke-induced oxidative stress and cellular senescence." (PMID 35744080, 2022). "Klotho was discovered in a transgenic mouse strain in 1997, and its mutation caused a syndrome similar to premature aging, including reduced lifespan, growth retardation, vascular calcification, genital atrophy, emphysema, and osteomalacia." (PMID 34070219, 2021). "This was a transversal, observational, case-control study where we examined demographics and functional characteristics, as well as telomere length and serum Klotho concentration, two conditions that have been associated with aging and some aging-associated diseases including emphysema." (PMID 32517728, 2020). "Importantly, klotho deficient mice exhibit the phenotype of emphysema." (PMID 28186975, 2017). "Homozygous mutant klotho (KL−/−) mice exhibited multiple phenotypes, which were similar to those observed during human aging, including develop spontaneous emphysema." (PMID 39930762, 2025). "Homozygous mutant klotho (KL−/−) mice had pulmonary emphysema and diverse aging phenotypes at an early stage." (PMID 39930762, 2025). "It remains unknown whether klotho affects AMPK activation during the development of emphysema." (PMID 28186975, 2017). "Recent data from research performed in the homozygous mutant klotho (KL[−/−]) mouse suggest that increased apoptosis of airway cells via the inhibition of the EGF-dependent pathway may be involved in the development of the aging lung process that includes emphysema." (PMID 23577098, 2013). "The length of telomeres and levels of Klotho was selected because telomere dysfunction and a marked decrease of circulating Klotho have been associated with COPD but their association in subclinical pulmonary emphysema was not clear." (PMID 32517728, 2020).
cognitive decline (25 papers, 2013 to 2026). "Reduced expression of klotho in CKD patients increases the risk of cognitive decline as high klotho expression is considered neuroprotective." (PMID 40950978, 2025). "Studies have shown that Klotho-deficient mice exhibit early aging, cognitive decline, and increased susceptibility to neurodegeneration, while overexpression of Klotho leads to enhanced cognitive function and increased lifespan." (PMID 40351444, 2025). "Overexpression of klotho using genetic approaches have provided convincing evidence that increasing klotho in the brain can enhance cognition and potentially reverse the cognitive-decline associated with ageing and AD." (PMID 34194816, 2021). "Longevity‐associated KL‐VS variants (haplotype including F352V and C370S) in the Klotho gene (KLOTHO) are also associated with protection against cognitive decline." (PMID 34197020, 2021). "Klotho (KL) is a transmembrane protein that protects against cognitive decline as well as other aging-associated phenotypes." (PMID 34172062, 2021). "We found that Klotho overexpression significantly improved cognitive decline, reduced Aβ burden, ameliorated neuronal and synaptic loss, and increased CBF in APP/PS1 mice." (PMID 32964663, 2020). "Specifically, poor non-verbal reasoning ability is seen in elderly females carrying the V/V genotype, suggesting that human Klotho-VS polymorphism is associated with cognitive decline and shortened life span." (PMID 29088855, 2017). "It was found that the rs2283368 and rs9526984 SNPs in the Klotho gene were associated with more than 7 years of cognitive decline." (PMID 29088855, 2017). "Higher plasma klotho concentrations were associated with a reduction of the aging-related cognitive decline in large longitudinal cohort." (PMID 26517365, 2015). "We further established that the tRF upregulated by Klotho knockout interacts with proteins involved in major RNA processing pathways, such as splicing and mRNA decay, providing the first functional evidence for the involvement of tRFs in Klotho-associated cognitive decline." (PMID 38862813, 2024). "Furthermore, low plasma Klotho concentrations have been shown to be independently associated with disability, cognitive decline, and mortality in older, community-dwelling persons." (PMID 35333903, 2022). "Although challenges remain, klotho stands as a potential therapeutic target for mitigating cognitive decline and promoting brain health across a range of neurodegenerative and cerebrovascular conditions." (PMID 41983942, 2026). "In the present study, we controlled for educational attainment to isolate the effects of APOE and Klotho genotype and its interaction with sex and age on cognitive decline." (PMID 39903109, 2025). "Our study suggests that routine testing of serum klotho can be considered in NAFLD patients for early detection of cognitive decline." (PMID 39563739, 2024). "Remarkably, short non-coding RNA transcripts, affected by Klotho KO, also exhibit parallel changes in aging and AD, reflecting an orchestrated transcriptional response shared by Klotho KO and aging-related cognitive decline." (PMID 38862813, 2024). "We provide the first experimental evidence of the functional involvement of tRFs in Klotho-related cognitive decline." (PMID 38862813, 2024). "On the other hand, we demonstrated a cognition enhancing role of Klotho in a surgical setting with the potential to reverse, or at least reduce, post-operative cognitive decline after cardiac surgery." (PMID 37693766, 2023). "In previous studies involving patients with cognitive dysfunction, reduced plasma Klotho level was independently correlated with the degree of cerebral WMHs and was accompanied by cognitive decline, especially vascular dementia." (PMID 31398214, 2019).
cognitive decline (continued). "We hypothesized that APOE homozygous ε4 carriers would exhibit more rapid cognitive decline and yield neuroanatomical changes with aging, while individuals with Klotho-VS heterozygosity would exhibit protective effects against such decline." (PMID 39903109, 2025). "Importantly, our study provides novel clinical evidence for the intermediary role of klotho in linking chronic hyperglycemia to cognitive decline." (PMID 38505757, 2024). "Furthermore, Klotho has been found to reduce neural damage and neurodegeneration, thus protecting against cognitive decline and contributing to life extension in humans." (PMID 37425590, 2023). "Our findings suggest that the Klotho protein, but not the KL-VS heterozygosity haplotype, differs in clinical stages of AD and is associated with cognitive decline and amyloid and tau burden." (PMID 36413367, 2022). "Serum klotho, as an anti-aging protein, may be involved in cognitive decline." (PMID 36819720, 2023). "The findings of this case-control study suggest that Klotho protein levels were associated with clinical stages of AD, cognitive decline, and amyloid and tau burden and that these outcomes were more clearly mediated by the protein directly rather than the KL-VS heterozygosity variant." (PMID 36413367, 2022). "However, the role of KL in the development of AD remains to be defined, as a recent study showed that a functional variant in KL, namely KL-VS, had no influence on cognitive decline in preclinical AD42." (PMID 31745181, 2019). "Thus, the association between increased FGF23 levels and dementia could be explained by the effects of the anti-aging protein klotho and enhancing the effects of klotho could potentially protect against cognitive decline and dementia." (PMID 30830941, 2019). "Therefore, the mitigating effect of KL-VShet+ on cognitive decline we observed in ε4 non-carriers can be partly attributed to klotho’s anti-oxidant and anti-inflammatory effects." (PMID 37107675, 2023).
Hyperglycemia (25 papers, 2013 to 2025). An increased concentration of glucose in the blood. "Our previous study demonstrated that the shedding of soluble Klotho was increased in hyperglycemia and caused a decrease in the amount of podocyte membrane-bound Klotho, affecting podocyte filtration functions." (PMID 39859443, 2025). "Finally, the apoptosis and heart damage caused by endotoxemia or hyperglycaemia in mice were alleviated by Klotho." (PMID 33123314, 2020). "For example, secreted or soluble Klotho in the serum has been shown to reduce neuronal loss and neurodegeneration, promote stem cells, and protects the heart from hyperglycemia-induced injury." (PMID 31001090, 2019). "Elevations in Klotho's levels contribute to the regulation of inflammation by inhibiting the pro-inflammatory response produced by hyperglycemia through the mechanism of NF-κB, which reduces kidney injury." (PMID 40119098, 2025). "Exogenous Klotho protein supplementation inhibits oxidative stress production and hyperglycemia, correlating with different kidney injury studies." (PMID 40119098, 2025). "By alleviating hyperglycemia-induced oxidative, ER and mitochondrial stress, klotho maintains neuronal integrity and function." (PMID 38505757, 2024). "Insulin resistance in trophoblastic cells, exacerbated by Klotho overexpression, leads to maternal hyperglycemia and disrupted nutrient transfer, contributing to fetal overgrowth (macrosomia) and increased risk of delivery complications." (PMID 39519193, 2024). "In cardiomyocytes exposed to hyperglycemia, it has been reported that Klotho plays a protective role both in vitro and in vivo, through the inactivation of ROS and NFκB-mediated inflammation." (PMID 37242170, 2023). "Klotho attenuates the inflammatory response induced by hyperglycemia by directly or indirectly regulating NF-κB, thereby reducing renal damage." (PMID 37143722, 2023). "Given that hyperglycemia contributes to DN pathogenesis, our study identified the impact of HG on KL expression in podocytes." (PMID 35480629, 2022). "Klotho G395A and C1818T polymorphisms are thus risk factors for the development of T2DM, elevated glycosylated hemoglobin and hyperglycemia." (PMID 36140700, 2022). "Klotho decreases hyperglycemia-induced oxidative stress, with resulting podocyte injury and apoptosis, through the inhibition of various signaling pathways, including insulin-like growth factor 1, protein kinase-1/2, and p38 mitogen-activated protein kinase." (PMID 34360633, 2021). "During hyperglycemia, the level of membrane-bound Klotho in renal tissue decreased, with an increase in the shedding of soluble Klotho, its higher presence in serum, and lower urinary excretion." (PMID 34360633, 2021). "This study demonstrated that Klotho overexpression significantly increased Lamin B1 levels, reduced p16, p21, and PAI-1 expression, and decreased the proportion of SA-β-Gal-positive cells in HK-2 cells exposed to AGE, underscoring Klotho’s protective role against senescence in hyperglycemia." (PMID 40823556, 2025). "Other studies have shown that overexpression of KL in pancreatic β-cells could decrease hyperglycemia and enhance glucose tolerance in db/db mice." (PMID 40018267, 2025). "Klotho may counteract the detrimental effects of hyperglycemia on cognition through diverse mechanisms." (PMID 38505757, 2024). "In addition to its effects on the autophagic pathway, klotho is also known to rescue hyperglycemia-mediated apoptosis of podocytes, glomerular endothelial cells, and renal tubular epithelial cells." (PMID 37143722, 2023). "Further, hyperglycemia and angiotensin II inhibited klotho gene expression." (PMID 33891667, 2021). "Therefore, the increase in glycolytic parameters that is induced by Klotho might enable podocytes to withstand the damaging effects of hyperglycemia." (PMID 34360633, 2021).
Hyperglycemia (continued). "In addition, it was shown that soluble Klotho has antioxidant properties and therefore may be involved in maintaining endothelial welfare, possibly reducing the burden of hyperglycemia by inhibiting oxidative stress and endothelial inflammation." (PMID 34603200, 2021). "In addition we investigated the potential effect of hyperglycemia on renal Klotho expression." (PMID 23945089, 2013). "Next, we analyzed whether hyperglycemia affects renal Klotho production in vitro." (PMID 23945089, 2013). "In summary, our research demonstrated that KL defended against hyperglycemia-induced podocyte injury in DN via suppressing TRPC6, which provided novel mechanistic insights for the role of KL in DN." (PMID 35480629, 2022). "Nevertheless, it has been suggested that hyperglycemia does not directly impact klotho production in isolated human renal tubular epithelial cells." (PMID 37143722, 2023). "This is supported by our in vivo and in vitro data showing that hyperglycemia per se does not affect renal Klotho production." (PMID 23945089, 2013). "Both the in vitro and in vivo mouse experiments revealed that renal Klotho production is not affected by hyperglycemia per se." (PMID 23945089, 2013). "Furthermore, hyperglycemia-induced modifications in intracellular metabolism and cellular events, including accumulation of AGEs, trigger the RAAS, activate PKC, and disrupt the amount of Klotho protein." (PMID 40119098, 2025). "Klotho protein was shown to overcome some negative effects of hyperglycemia." (PMID 34360633, 2021). "Long-term hyperglycemia in diabetic Ins2Akita mice (characterized by increased HbA1c levels [12.9 ± 0.3% (3 months) and 11.3 ± 2.0% (8 months)], p < 0.05 vs. non-diabetic mice) did not affect renal Klotho mRNA expression." (PMID 23945089, 2013). "Furthermore, hyperglycemia does not affect renal Klotho production." (PMID 35053218, 2022). "Furthermore, hyperglycemia per se does not affect renal Klotho production." (PMID 23945089, 2013).
Stroke (23 papers, 2015 to 2025). Sudden impairment of blood flow to a part of the brain due to occlusion or rupture of an artery to the brain. "Further prospective studies are requisite to investigate the impact of serum klotho protein levels on Stroke and determine the causal relationship." (PMID 40452763, 2025). "Even after eliminating all possible confounding factors, this negative correlation remained highly significant in the fully adjusted model (p < 0.05), with a 32% reduction in the risk of having stroke for every 1,000 pg./ml increase in klotho concentration." (PMID 40452763, 2025). "Further studies are needed to explore potential associations between Klotho and autophagy in stroke." (PMID 34737707, 2021). "Our study is the first one to examine KLOTHO SNPs and mortality in elderly community-dwelling subjects and two polymorphisms were associated with the main events that led to death, i.e., stroke and myocardial infarction." (PMID 32444684, 2020). "Klotho gene single nucleotide polymorphism (rs650439) has also been report to be associated with differing levels of circulating klotho and the onset of stroke." (PMID 30791885, 2019). "In fact, previous studies demonstrated correlations between human klotho polymorphisms and bone mineral density, glucose metabolism, cognitive function, cardioembolism, coronary artery diseases, and stroke." (PMID 30595559, 2018). "Furthermore, lower serum klotho levels are independently associated with a higher prevalence of stroke." (PMID 40452763, 2025). "Whether serum klotho levels demonstrate an independent association with stroke risk beyond traditional cardiovascular risk factors." (PMID 40452763, 2025). "In addition, high Klotho concentration was associated with a reduced risk of developing stroke and macroangiopathies in clinical study." (PMID 31398214, 2019). "We hypothesized that the loss of endogenous Klotho with advanced age increases the susceptibility of brain cells to ischemia through the induction of oxidative stress and neuroinflammation and worsens neurological outcomes in senile stroke patients." (PMID 29403373, 2017). "Since the relationship between serum klotho and Stroke remains rather ambiguous, this research probed into the potential correlation between serum klotho concentration and Stroke." (PMID 40452763, 2025). "Emerging evidence from these investigations and subsequent human studies reveals that klotho’s unique neuroprotective mechanism against stroke pathogenesis appears to be multifactorial." (PMID 40452763, 2025). "After adjusting for models 2 and 3, Klotho levels were significantly associated with the prevalence of CHF (OR 0.64; 95% CI 0.54–0.77) and stroke (OR 0.84; 95% CI 0.71–1.00)." (PMID 35509269, 2022). "In this study, we found that the CSF concentration of klotho in stroke patients decreased, positively correlated with the CSF concentration of irisin in stroke patients." (PMID 34306305, 2021). "Using ELISA, we found that the CSF irisin concentration and the CSF klotho concentration derived from stroke patients were lower than those derived from controls (P < 0.05)." (PMID 34306305, 2021). "The results demonstrated that stroke patients showed a positive correlation between their CSF irisin concentration and klotho concentration." (PMID 34306305, 2021). "Given the known protective function of klotho in cardiovascular disease, these findings suggest a possible link between genetic variation in klotho, circulating klotho concentration, and the onset of stroke." (PMID 30595559, 2018). "Klotho has become a promising therapeutic target for aging-related disorders, including neurodegeneration and stroke." (PMID 29403373, 2017). "Correlation analyses were then performed to investigate the association of CRP, homocysteine and Klotho biomarkers with the occurrence of previous vascular events (CAD, MI and stroke) at baseline." (PMID 28076518, 2016).